MT-ND1 (mitochondrially encoded NADH:ubiquinone oxidoreductase core subunit 1)
Description:
Core subunit of the mitochondrial membrane respiratory chain NADH dehydrogenase (Complex I) which catalyzes electron transfer from NADH through the respiratory chain, using ubiquinone as an electron acceptor. Essential for the catalytic activity and assembly of complex I.
Synonyms: ND1; NAD1; formerly MTND1
Tractability: Small molecule: an approved drug acts on it; a structure with a bound ligand is known. Antibody: UniProt predicts a signal peptide or a membrane-spanning region.
Target class: Enzyme; Oxidoreductase
Safety:
Unwanted effects reported when the protein is acted on. In parentheses: how it was acted on, where the effect was seen, and who reports it.
Parkinsonian motor deficits (inhibition; source: AOP-Wiki)
Gene: Protein-coding gene on chromosome MT (3,307 to 4,262, forward strand). Ensembl gene ENSG00000198888.
Subcellular location: Mitochondrion inner membrane
Pathways (Reactome):
Metabolism: Complex I biogenesis; Respiratory electron transport
Metabolism of proteins: Mitochondrial protein degradation; Mitochondrial translation termination
Gene Ontology:
Molecular function: NADH dehydrogenase (ubiquinone) activity; protein binding; NADH dehydrogenase activity
Biological process: mitochondrial electron transport, NADH to ubiquinone; mitochondrial respiratory chain complex I assembly; aerobic respiration; proton motive force-driven mitochondrial ATP synthesis; proton transmembrane transport
Cellular component: mitochondrial inner membrane; mitochondrial membrane; mitochondrion; respiratory chain complex I; membrane
Gene-disease validity (ClinGen):
ClinGen rates the evidence that MT-ND1 causes each of these diseases.
Leigh syndrome (mitochondrial): Definitive. A progressive neurological disease defined by specific neuropathological features associating brainstem and basal ganglia lesions.
mitochondrial disease (mitochondrial): Definitive.
Homologues: Orthologues: chimpanzee MT-ND1 (95% identical), macaque ND1 (86% identical), rabbit MT-ND1 (78% identical), mouse mt-Nd1 (77% identical), guinea pig MT-ND1 (76% identical), pig ND1 (76% identical), rat Mt-nd1 (75% identical), zebrafish mt-nd1 (66% identical), tropical clawed frog ND1 (64% identical), Drosophila melanogaster mt:ND1 (48% identical), Caenorhabditis elegans ND1 (33% identical).
Diseases named in the same sentence as MT-ND1 in open-access papers:
MT-ND1 is named in the same sentence as 65 diseases in open-access papers, as found by Europe PMC text mining. Sharing a sentence is not in itself a finding about the gene and the disease. The quoted sentences say what the papers report.
Leber hereditary optic neuropathy (13 papers, 2015 to 2024). Leber's hereditary optic neuropathy (LHON) is a mitochondrial neurodegenerative disease affecting the optic nerve and often characterized by sudden vision loss in young adult carriers. "These include the severe mutation in the tRNALys gene, m.8363G>A, and the three milder yet prevalent Leber's hereditary optic neuropathy (LHON) mutations in the MT-ND1 (m.3460G>A), MT-ND4 (m.11778G>A) and MT-ND6 (m.14484T>C) mitochondrial genes." (PMID 25909222, 2015). "Similarly, the MT-ND1 V144I variant is associated with Leber hereditary optic neuropathy (LHON, MIM #535000)." (PMID 33300029, 2021). "The MT-ND1 gene has been examined in association with several diseases including recurrent pregnancy loss, colorectal cancer, bladder cancer, Parkinson’s disease, and contradicting results have been published regarding it’s possible effect on multiple sclerosis and Leber’s optic atrophy." (PMID 30684245, 2019). "Furthermore, MT-ND1, MT-ND6 gene mutations and a 4-base-pair deletion in the cytochrome B gene were found in patients with parkinsonism associated with optic atrophy, myoclonic epilepsy and SLEs, typical PMDs red flags." (PMID 38069070, 2023). "For example, mutations in MT-ND1 and MT-ND4 can cause Leber hereditary optic neuropathy (LHON), a disease characterized by bilateral, painless central vision loss in early to late adulthood resulting from the specific degeneration of retinal ganglion cells in the optic nerve." (PMID 26839416, 2016).
colorectal cancer (5 papers, 2019 to 2024). A primary or metastatic malignant neoplasm that affects the colon or rectum. "Mutations in MT-ND1 account for nearly 40% of mtDNA mutations in colorectal cancer, correlate with breast cancer, and promote lung tumorigenesis." (PMID 39594421, 2024). "Additional reports described associations between mutations in the MT-ND1 gene and thyroid tumors, ovarian carcinoma, colorectal cancer, and prostate cancer." (PMID 31810328, 2019). "We aimed to find out whether the content and variants of circulating MT-ND1 could be a potential biomarker for colorectal cancer." (PMID 33823124, 2021). "In conclusion, the content and variants of circulating MT-ND1 may become a versatile tool for the diagnosis and monitoring of colorectal cancer." (PMID 33823124, 2021). "We sought to determine if mutations in circulating MT-ND1 could be a potential biomarker for colorectal cancer." (PMID 33823124, 2021).
Leigh syndrome (4 papers, 2015 to 2024). "For example, the homoplasmic variant 3481G > A located in the MT-ND1 gene is a known pathological variant associated with MELAS disease (mitochondrial encephalomyopathy with lactic acidosis and stroke-like episodes), progressive encephalomyopathy, or Leigh syndrome." (PMID 39802950, 2024).
breast carcinoma (3 papers, 2005 to 2024). "The change in the position m.T3398C of MT-ND1 described in breast cancer is also observed in patients with progressive external ophtalmoplegy and cardiomyopathy." (PMID 24414975, 2014).
cardiomyopathy (3 papers, 2014 to 2025). A disease of the heart muscle or myocardium proper. "Thirteen patients from 10 families with cardiomyopathy harbored three different mutations as follows: MTTK m.8363G > A (one family), MTND1 m.3943G > A (one family), and MTTL1 m.3243 A > G mutations (eight families)." (PMID 40382647, 2025).
diabetes mellitus (3 papers, 2021 to 2025). A metabolic disorder characterized by abnormally high blood sugar levels due to diminished production of insulin or insulin resistance/desensitization. "Non-synonymous mtDNA variants in the MT-ND1 gene, which is found in patients with diabetes." (PMID 39835172, 2025).
lactic acidosis (3 papers, 2021 to 2024). Metabolic acidosis characterized by the accumulation of lactate in the body. "MT-ND1 was the core mitochondrial-encoded subunit of mitochondrial respiratory complex I. Besides cancer, MT-ND1 is also associated with mitochondrial encephalopathy, lactic acidosis, and stroke-like episodes (MELAS) and optic nerve disease." (PMID 33823124, 2021).
MELAS (3 papers, 2014 to 2021). "Mutations in human MT-ND1 are associated with the appearance of several severe syndromes, including LHON and MELAS." (PMID 24560811, 2014).
Sepsis (3 papers, 2020 to 2024). Sepsis is defined as life-threatening organ dysfunction caused by a dysregulated host response to infection. "This was accompanied by lower mitochondrial DNA copy numbers (p < 0.001), mtND1 expression (p < 0.001) and cellular ATP content (p < 0.001) in sepsis patients." (PMID 33273525, 2020). "Furthermore, we identified that the expression of mt-ND1, mt-CO1, and mt-ATP6 was associated with sepsis-related death, which had been confirmed by AUC under ROC calculations." (PMID 39113822, 2024). "Remarkably, in our study, mitochondrial function-related indicators, including mt-CO1, mt-ND1, and mt-ATP6, exhibited significantly higher discriminative capabilities for predicting the clinical outcomes of sepsis-associated lethality compared to traditional laboratory indicators." (PMID 39113822, 2024). "Univariate analysis revealed a significant reduction in the expression of mt-CO1, mt-ND1, and mt-ATP6 in patients with sepsis." (PMID 39113822, 2024). "In comparison to other laboratory parameters, the expression levels of mt-CO1, mt-ND1, and mt-ATP6 demonstrate notable potential in predicting the prognosis of pediatric sepsis." (PMID 39113822, 2024). "Notably, when compared to other laboratory parameters, the expression levels of mt-CO1, mt-ND1, and mt-ATP6 demonstrate promising potential for assessing the prognosis of pediatric sepsis." (PMID 39113822, 2024).
COVID-19 (2 papers, 2023 to 2024). A disease caused by infection with severe acute respiratory syndrome coronavirus 2. "The polymerase chain reaction (PCR) showed mitochondrial DNA encoding the cytochrome electron transport complex component NADH dehydrogenase 1 (MT-ND1) was detectable in the plasma of most COVID-19 as well as ICU-ARDS patients." (PMID 37031181, 2023).
hepatocellular carcinoma (2 papers, 2023 to 2024). A malignant tumor that arises from hepatocytes. "Likewise, heteroplasmic mutations in MT-ND1 are linked to hepatocellular carcinoma." (PMID 39594421, 2024). "In an earlier study, the G3842A mutation in MT‐ND1 that we detected in the metastatic‐TNBC patients, was found to be associated with hepatocellular carcinoma progression." (PMID 37810173, 2023).
leprosy (2 papers, 2013 to 2024). Leprosy is a chronic infectious disease affecting primarily the skin and peripheral nervous system. "Notably, six variants were exclusively found in both clinical poles of leprosy, including m.4158A>G and m.4248T>C in MT-ND1, m.13650C>A, m.13674T>C, m.12705C>T and m.13263A>G in MT-ND5, of which there are no previous reports in the global literature." (PMID 38493220, 2024). "Other mRNAs were also less expressed in leprosy patients when compared to non-leprous samples, such as Bad, IL10, IL12 as well as several mitochondrial genes (mtCOX2, mtND1, mtND3 mtND5 mtATP6, and mtCYB)." (PMID 23798993, 2013).
melanoma (2 papers, 2017 to 2023). A malignant, usually aggressive tumor composed of atypical, neoplastic melanocytes. "We found that in the human melanoma 1205Lu cell line, as well as in primary tumors, the expression levels of the mitochondrial genes MT-ND1 and MT-ND4 were downregulated." (PMID 36672229, 2023).
acute leukemia (1 paper, 2024). A clonal (malignant) hematopoietic disorder with an acute onset, affecting the bone marrow and the peripheral blood. "Similarly, A/G transition in nucleotide position 4216 of the MT-ND1 gene was observed in acute leukemia induced by clonal myeloid disorders." (PMID 39802950, 2024).
amyloidosis (1 paper, 2021). A disorder characterized by the localized or diffuse accumulation of amyloid protein in various anatomic sites. "A group of mitochondria proteins related to energy generation were observed in these same pathways/hubs that were previously shown to have AD/dementia/amyloidosis associations including MT-ND1, MT-ND6, and MT-CO1." (PMID 33946285, 2021).
bipolar disorder (1 paper, 2015). A disorder of the brain that causes unusual shifts in mood, energy, activity levels and the ability to carry out day-to-day tasks. "The mtDNA 5178 A>C variant of the complex I subunit 1 (MT-ND1) gene was analyzed in leukocytes and the 5178C genotype was significantly more common in bipolar disorder compared to controls in cases with a maternal family history." (PMID 25946463, 2015).
cataract disease (1 paper, 2022). "Among the upregulated Mendelian cataract disease-associated genes were several crystallins (CRYAB and CRYBB2) and mitochondrial encoded genes (MT-ATP6, MT-ND1, and MT-CO2)." (PMID 35348588, 2022).
cervical cancer (1 paper, 2023). A primary or metastatic malignant neoplasm involving the cervix. "Based on these elements, a study was conducted to determine the alterations in the mtND1 gene and evaluate their association with the development of precancerous lesions and cervical cancer." (PMID 37873540, 2023). "The analysis also revealed that the level of ROS production was higher in cervical cancer tissues and in all cases characterized by mtND1 mutations." (PMID 37873540, 2023). "The lowest mRNA expression of ND1 was detected in cervical cancer cases and in all samples in which mtND1 mutations were identified." (PMID 37873540, 2023).
E. coli infection (1 paper, 2022). "Moreover, expression of the mtND1-mtND6 genes assessed by real-time quantitative PCR increased upon E. coli infection, both with and without EGTA pretreatment, which was restored by pretreatment with NAC, BAPTA-AM, or 2-APB." (PMID 36430657, 2022).
Obesity (1 paper, 2023). Accumulation of substantial excess body fat. "Previously, it has been shown that bariatric surgery after 6 months reduced urinary mtND1 and mtCOX3 copy numbers, as well as serum mtCOX3 copy numbers, only in patients with obesity with T2D." (PMID 37760955, 2023).
obsessive-compulsive disorder (1 paper, 2015). A disorder characterized by the presence of persistent and recurrent irrational thoughts (obsessions), resulting in marked anxiety and repetitive excessive behaviors (compulsions) as a way to try to decrease that anxiety. "The expression of other 5 protein-coding mitochondrial-encoded genes, MT-ND1, MT-ND5, MT-CO3, MT-ATP6, MT-ATP8, was found associated with the maternal psychopathology diagnosis of maternal obsessive compulsive disorder, maternal weight and with infant birth measures." (PMID 26418562, 2015).
osteosarcoma (1 paper, 2024). A usually aggressive malignant bone-forming mesenchymal neoplasm, predominantly affecting adolescents and young adults. "Osteosarcoma 143B cybrids were generated from a negative control without any pathologic mutation (Genbank: OQ803246, Oc), a positive control containing the m.3460G > A LHON pathologic mutation in MT-ND1 (GenBank: JX401416, O3460), and the patient (GenBank: OQ803247, O3734)." (PMID 38582886, 2024).
tumor (16 papers, 2014 to 2023). "Interestingly, one of the tumour samples (T10) had several mutations in mtDNA: MT‐ND1, MT‐ND4 and MT‐ATP6." (PMID 37317665, 2023). "The genomic DNA of tumor tissues was used to detect the mutation of MT-ND1." (PMID 33823124, 2021). "However, in the tumor antecedent, CZN5 tumor 1, the mt-ND1 (3274 T>TA) mutation frequency rose to 100% demonstrating that all mtDNA copies tested by NGS, from this tumor, possessed the mtND1(3274 T>TA) SNP variant in the same position in the mitochondrial coding region." (PMID 32010429, 2020). "Significant decrease in the relative expression of the mitochondrial genes Tomm20 and MT-ND1 was observed in tibialis anterior samples from tumour-bearing mice." (PMID 33975599, 2021). "However, five genes (MT-CO1, MT-CYB, MT-DLOOP1, MT-ND1 and MT-ND5) not only presented germline variants, but also different somatic variants exclusive to tumor and internal control groups, indicating a possible association of such genes and variants with tumor development." (PMID 31673122, 2019). "The mtND-1 copy number in PBMCs of the primary gastrointestinal cancer patients without anti-tumor treatments was lower than that in healthy donors, consistent with the decrease of ΔΨm and ATP." (PMID 36765353, 2023). "Expression of Tomm20 and MT-ND1 was reduced in the tibialis anterior muscle of tumour-bearing mice, while the expression of COXIV and OPA1 was reduced in the gastrocnemius muscle of tumour-bearing mice." (PMID 33975599, 2021).
cancer (10 papers, 2008 to 2025). A tumor composed of atypical neoplastic, often pleomorphic cells that invade other tissues. "In human cancers, three variants, Y30H, Y43C, A64V, and few others, have been observed that can alter the structure and function of the mtND1 protein." (PMID 37544976, 2023). "Complementation of a truncative mutation in the gene encoding MT-ND1, showed that a functional enzyme was required to perform the glycolytic shift during the hypoxia response and to induce a Warburg profile in vitro and in vivo, fostering cancer progression." (PMID 24280190, 2013). "Mutations in MT-ND1 might cause an alteration of the electron transport components and damage the normal electron flow, leading to an increase of superoxidase radical generation and increase oxidative stress in various types of cancer cells." (PMID 33823124, 2021). "RNA sequencing revealed the downregulation of five genes, three of which were mitochondrial genes—MT-CYB, MT-ND1, and MTND2P28—implicated in cancer progression." (PMID 40974979, 2025). "In addition, six transcripts (MT-ATP6, MT-CO1, MT-CYB, MT-ND1, MT-ND6, and MT-RNR1) were quantified in 62 cancer tissues by real-time RT-PCR." (PMID 18842121, 2008). "Also among the upregulated genes were mitochondrial protein coding genes (MT-ND3, MT-ND4L, MT-ND4, MT-ND2, MT-CYB, MT-ND1, MT-CO1 etc), which may be as a result of the elevated metabolism characteristic of cancer cells to sustain their survival." (PMID 29132323, 2017).
infection (10 papers, 2014 to 2025). The state of being infected such as from the introduction of a foreign agent such as serum, vaccine, antigenic substance or organism. "Our results showed that infection with E. coli increased the levels of proteins encoded by mtND1-mtND6 proteins and that this increase was reduced by NAC, BAPTA-AM, or 2-APB." (PMID 36430657, 2022). "Thus, assessing the exact expression of particular genes, such as mt-ND1, mt-CO1, and mt-ATP6, might serve as a more precious role in determining related clinical outcomes of infection." (PMID 39113822, 2024).
mitochondrial disease (2 papers, 2018 to 2021). "Five lymphoblastoid cell lines derived from mitochondrial disease patients harboring point mutations in mtND1, mtND4, or mtATP6 were characterized in two high throughput assays assessing mitochondrial function." (PMID 29587845, 2018). "Mitochondrial deletions are typical of mitochondrial disease, therefore we examined whether mitochondrial deletions differed in ASD compared to controls by quantifying the copy number of the mitochondrial gene MT-ND1 relative to MT-ND4; the latter resides in the major mitochondrial deletion arc." (PMID 34381777, 2021).
MT-ND1 also shares sentences with these, for which no sentence is quoted: cyst (11 papers); echinococcosis (4); lymphoma (3); Parkinson disease (3); fascioliasis (2); leukemia (2); Mitochondrial encephalopathy (2); asthma (1); atherosclerosis (1); bladder cancer (1); candidiasis (1); co-infection (1); Cognitive impairment (1); deafness (1); dementia (1); epilepsy (1); Epileptic encephalopathy (1); follicular thyroid carcinoma (1); gastric cancer (1); genetic diseases (1); Hypertension (1); liver cancer (1); liver disease (1); metabolic disease (1); mitochondrial encephalomyopathy (1); multiple sclerosis (1); nematode infection (1); optic atrophy (1); optic neuropathies (1); ovarian carcinoma (1).
A further 9 diseases each share a sentence with MT-ND1 in 1 paper.